RNU6-1274P (RNA, U6 small nuclear 1274, pseudogene)
Gene: Small nuclear RNA gene on chromosome 10 (96,743,167 to 96,743,273, forward strand). Ensembl gene ENSG00000207287.
Homologues: Orthologues: chimpanzee U6 (99% identical), macaque U6 (92% identical), mouse Gm25337 (90% identical), rabbit U6 (88% identical), mouse Gm22229 (86% identical), guinea pig U6 (83% identical). Paralogues in human: RNU6-1127P (90% identical), RNU6-166P (90% identical), RNU6-242P (90% identical), RNU6-41P (90% identical), RNU6-11P (89% identical), RNU6-15P (89% identical), RNU6-37P (89% identical), RNU6-43P (89% identical), RNU6-1011P (88% identical), RNU6-1131P (88% identical), RNU6-12P (88% identical), RNU6-1331P (88% identical), and 1287 more.